EFEMP1 (EGF-like fibulin extracellular matrix protein 1)
Diseases named in the same sentence as EFEMP1 in open-access papers (continued):
Sharing a sentence is not in itself a finding about the gene and the disease.
macular degeneration (14 papers, 2013 to 2024). Loss of vision in the central portion of the retina (macula), secondary to retinal degeneration. "The mutation p.R345W in the EFEMP1 gene causes an inherited macular degeneration clinically similar to AMD." (PMID 34360950, 2021). "The in vivo and in vitro studies showed that the genetic ablation of C5 is not sufficient to prevent the formation of basal deposits underneath the RPE in a mouse model of the inherited EFEMP1-associated macular degeneration." (PMID 34001980, 2021). "To address this question, in the current study we assessed the role of C5 in the formation of sub-RPE deposits in a mouse model of the EFEMP1-associated macular degeneration in vivo and in vitro." (PMID 34001980, 2021). "We have previously demonstrated that C3 blockage prevents the formation of sub-RPE deposits in a mouse model of EFEMP1-associated macular degeneration." (PMID 34001980, 2021). "Concurrently, EFEMP1 was associated with inherited forms of macular degeneration." (PMID 25987128, 2015). "In eight sporadic cases, we detected eight heterozygous rare sequence variants in six macular degeneration genes (CFH; FBLN1, OMIM 135820; FBLN3/EFEMP1, OMIM 601548; FBLN5, OMIM 604580; HMCN1, OMIM 608548; FBN2, OMIM 612570)." (PMID 27007659, 2016). "Previous research has confirmed that EFEMP1 bind to TIMP-3 in macular degenerative diseases; they colocalize in vivo and form a complex in situ." (PMID 25987128, 2015). "For instance, EFEMP1-associated macular degeneration, caused by the dominant mutation p.R345W in the EGF-containing fibulin-like extracellular matrix protein 1 (EFEMP1) gene shares clinical features with AMD, including the early appearance of sub-RPE deposits or drusen in the macula." (PMID 34001980, 2021). "Secondly, Efemp1 KO mice do not develop an early-onset macular degeneration phenotype, making it unlikely that loss of fibulin-3 triggers the pathology." (PMID 32911658, 2020). "We focused on validation of EFEMP1 expression in the cochlea because a gene encoding an effector of EGF-mediated cell signaling causes progressive hearing loss, and single mutations in the EFEMP1 gene cause two inherited forms of macular degeneration." (PMID 31185063, 2019). "Yeast 2-hybrid (Y2H) screens of a retinal pigment epithelium/choroid library derived from aged donors using CFH SCR7 baits detected an interaction with EFEMP1/Fibulin 3 (Fib3), which is the locus for an inherited macular degeneration and also accumulates basal to macular RPE in AMD." (PMID 23840815, 2013). "In contrast, targeted inactivation of Efemp1 in mice resulted in premature aging, shortened lifespan and reduced reproductive capacity compared to wild-type mice, without signs of macular degeneration." (PMID 30102696, 2018).
pleural mesothelioma (13 papers, 2013 to 2022). A neoplasm that arises from the mesothelial cells of the pleura. "EFEMP1 has been shown to be upregulated in pleural mesothelioma and is regarded as a potential biomarker for the disease." (PMID 32280689, 2020).
Inguinal hernia (12 papers, 2015 to 2025). Protrusion of the contents of the abdominal cavity through the inguinal canal. "In the female group, the EFEMP1 rs2009262 TC/CC genotype was significantly associated with inguinal hernia (OR: 1.71, 95% CI: 1.12-2.62, p = 0.01)." (PMID 37082733, 2023). "Conversely, among females with BMI < 24 kg/m2, carriers of EFEMP1 rs2009262 had a 1.83-fold increased risk of inguinal hernia (OR: 1.83, 95% CI: 1.10-3.05, p = 0.02)." (PMID 37082733, 2023). "After stratifying BMI, overweight males with EFEMP1 rs2009262 TC/CC genotype exhibited a higher risk of inguinal hernia (OR: 1.31, 95% CI: 1.07 - 1.61, p = 0.01)." (PMID 37082733, 2023). "The WT1 rs3809060 locus exhibited an association with hernia risk among male participants, while overweight (BMI ≧ 24 kg/m2) males carrying the TC/CC genotype of the EFEMP1 rs2009262 variant were found to be at an increased risk of developing inguinal hernia." (PMID 37082733, 2023). "One of the eight POP variants, rs3791675 at EFEMP1, associates with traits with proposed collagen pathophysiology, i.e. inguinal hernia, ventral hernia and carpal tunnel syndrome." (PMID 32184442, 2020). "Variants in the EFEMP1 locus have been associated with a variety of human traits and diseases, such as human height, forced vital capacity, inguinal hernia, and chronic venous disease (CVD)." (PMID 30102696, 2018). "These loci for inguinal hernia susceptibility are EFEMP1, WT1, EBF2, and ADAMTS6." (PMID 31024927, 2019). "However, IV SNPs for the EFEMP1 protein (rs3791679, rs9309272, and rs3791663) were significantly associated with the risk of inguinal hernia, which could be a complication of DD." (PMID 39533633, 2024). "Moreover, the IV SNPs for EFEMP1 protein were associated with inguinal hernia, which could be a complication of DD, suggesting that they had a pleiotropic effect." (PMID 39533633, 2024). "In the female group, genotype EFEMP1 rs2009262 TC/CC and COPD (OR: 2.34, 95% CI: 1.33 - 4.11, p = 0.003) were associated with greater incidence of inguinal hernia." (PMID 37082733, 2023). "This hospital-based case-control study identified preferential SNPs with increased susceptibility to adult-onset inguinal hernia; EFEMP1 rs2009262 in females and WT1 rs3809060 in males, specifically in association with direct-type inguinal hernia." (PMID 37082733, 2023). "EFEMP1 knockout mice show depleted elastic fibres within fascia and invariably develop inguinal hernia, adding further strength to the evidence for its importance in AWH pathophysiology." (PMID 36584111, 2022). "Jorgenson and colleagues previously identified 4 inguinal hernia susceptibility loci purported to result in reduced MMP activity: WT1, EFEMP1, EBF2 and ADAMTS6." (PMID 36584111, 2022). "We identified four novel inguinal hernia genetic susceptibility loci near the genes WT1, EFEMP1, EBF2 and ADAMTS6, and confirmed those associations in an independent cohort." (PMID 26686553, 2015). "EFEMP1 knockout mice develop both direct and indirect inguinal hernias, have reduced elastic fibres in fascia and display signs of early aging." (PMID 26686553, 2015). "A greater prevalence of the EFEMP1 rs2009262 TC/CC genotype (36.6% vs. 32.6%, p = 0.01) and the WT1 rs3809060 GT/TT genotype (48.1% vs. 44.1%, p = 0.02) was found in the inguinal hernia group than in the control group." (PMID 37082733, 2023).
pancreatic adenocarcinoma (12 papers, 2011 to 2024). "Changes in EFEMP1 expression have previously been linked to cancers such as lung, liver, breast, prostate, nasopharyngeal, and pancreatic adenocarcinoma." (PMID 38324544, 2024). "In pancreatic adenocarcinoma EFEMP1 expression promoted tumour grow in vivo and rescued tumour cells from apoptosis induced by 5-fluorouracil, gemcitabine, and irinotecan." (PMID 24804215, 2014). "In pancreatic adenocarcinoma, EFEMP1 was found significantly up-regulated in the highly metastatic cell line and promoted xenograft formation in vivo." (PMID 24236050, 2013). "On the other hand, EFEMP1 promoted tumor growth in pancreatic adenocarcinomas and acted as an oncogene." (PMID 24345474, 2013). "In addition, pancreatic adenocarcinoma cells, EFEMP1 over-expression was shown to promote xenograft formation." (PMID 21955618, 2011). "It is reported that misfolded EFEMP-1 accumulates within endoplasmic reticulum and up-regulates VEGF expression in pancreatic adenocarcinoma." (PMID 24919117, 2014). "Additionally, MAPK signaling related molecules (MAPK1, 14-3-3-gamma, RhoA) and the EGF ligand EFEMP1, which has been shown to activate MAPK signaling in pancreatic adenocarcinomas, were enriched in STM compared to YST/TER." (PMID 37726478, 2023).
bladder cancer (11 papers, 2014 to 2025). "In conclusion, our analysis confirmed that the ceRNA network YARS1‐hsa‐miR‐148b‐3p/hsa‐miR‐191‐5p‐NFIA/EFEMP1/TRAK2/PAFAH1B1 is associated with bladder cancer prognosis." (PMID 38506098, 2024). "METTL1 can affect the m7G tRNA-mediated codon-specific translation of EGFR/EFEMP1 by regulating tRNA m7G modification to regulate bladder cancer cell behavior." (PMID 40360483, 2025). "For example, METTL1 is associated with poor prognosis in bladder cancer, and it regulates the translation of EGFR/EFEMP1 by modifying certain tRNAs to inhibit the proliferation, migration and invasion of bladder cancer cells." (PMID 40443650, 2025). "In bladder cancer, EFEMP1 was also reported to possess an oncogenic role and to promote bladder cancer metastasis." (PMID 30754729, 2019). "Recently, upregulation of EFEMP1 has been found in bladder cancer, correlating with increased tumour invasiveness, while knockdown of EFEMP1 restored the invasive and migratory potential." (PMID 30008265, 2018). "Fibulin-3 (EFEMP1), a glycoprotein of the extracellular matrix that is encoded by the gene EFEMP1, has been nominated as one of the potential mediators of muscle invasion in bladder cancer." (PMID 35473807, 2022). "For example, EFEMP1 protein expression was upregulated by METTL1-mediated m7G tRNA modification, which in turn leads to bladder cancer development." (PMID 36973645, 2023). "EFEMP1 methylation assay discriminated PCa from normal prostate tissue (NPT; P < 0.001, Kruskall–Wallis test) and renal and bladder cancers (96% sensitivity and 98% specificity)." (PMID 25211630, 2014).
malignant glioma (11 papers, 2011 to 2025). A grade III or grade IV glioma arising from the central nervous system. "Anti-cancer effects have also been confirmed in vitro through characterization of EFEMP1 function in cell lines derived from human lung cancers, nasopharyngeal carcinomas, and malignant gliomas." (PMID 25594013, 2014). "We utilized various human malignant glioma cell lines and primary cultures to examine the mechanisms of EFEMP1 tumor suppression." (PMID 21955618, 2011). "As a protein functioning in the extracellular milieu, given its potential tumor-suppressive role, there is an interest to develop EFEMP1 into a new therapeutic agent for patients with malignant glioma." (PMID 21955618, 2011). "Results from microarray analyses revealed that EFEMP1 is up-regulated by transcription factor PAX6 - a tumor suppressor in malignant gliomas." (PMID 21955618, 2011). "We started an investigation of EFEMP1 using the human malignant glioma cell line U251HF, which is highly tumorigenic and forms GBM-like infiltrating necrotic tumors in i.c. xenograft model systems." (PMID 21955618, 2011). "One study reported that EFEMP1 was upregulated in malignant gliomas and may play a role in the aggressive nature of these tumors." (PMID 30754729, 2019). "In this study, we sought to evaluate the role of EFEMP1 in malignant glioma biology." (PMID 21955618, 2011). "EFEMP1 can increase the expression and activity of MMP-2 and MMP-9 in malignant gliomas, a finding which is somewhat similar to the results of our study." (PMID 25987128, 2015). "This study showed that EFEMP1 repressed AKT activity and phosphorylation of multiple AKT substrates in human malignant glioma cells." (PMID 21955618, 2011). "Our data revealed that EFEMP1 is a favorable prognostic factor for GBM, has a tumor-suppressive effect in malignant glioma cells, and acts in the extracellular compartment via independent blocking of EGFR and AKT signaling pathways while also repressing VEGFA-induced angiogenesis." (PMID 21955618, 2011).
Pleural effusion (11 papers, 2015 to 2025). The presence of an excessive amount of fluid in the pleural cavity. "The extracellular matrix protein fibulin-3/EFEMP1 accumulates in the pleural effusions of MPM patients and has been proposed as a prognostic biomarker of these tumors." (PMID 36303838, 2022).
endometrial carcinoma (10 papers, 2013 to 2025). A malignant tumor arising from the epithelium that lines the cavity of the uterine body. "Here, we reported that the expression of EFEMP1 was conversely associated with ERα in endometrial carcinoma tissues." (PMID 27015552, 2016). "We found that promoter methylation of EFEMP1 in endometrial carcinomas was associated with lower value of IRS (mean 1.8) as compared to carcinomas with unmethylated EFEMP1 (mean 4.080) (P = 0.0333)." (PMID 23840707, 2013). "In this study, we firstly reported that EFEMP1 was commonly lost in endometrial carcinoma, which was mainly caused by promoter hypermethylation." (PMID 23840707, 2013). "Future studies should elucidate the potential use of EFEMP1 methylation as a molecular biomarker to predict the risk of endometrial carcinoma development and its association with hormonal signaling such as estrogen." (PMID 23840707, 2013). "Our observations showed in endometrial carcinoma, down-regulated EFEMP1 expression was largely caused by aberrant methylation and significantly suppressed cell proliferation, invasion and migration." (PMID 23840707, 2013). "Furthermore, a cross comparison of common DEGs across the three datasets revealed that TOP2A, ASPM, FOXL2 and EFEMP1 were potential biomarkers for distinguishing endometrial cancer, and this was significantly associated with the survival ratios among patients." (PMID 32555395, 2020). "To investigate whether the change in EFEMP1 expression of EC was associated with any of the available clinical characteristics, we studied the association of EFEMP1 expression levels with the clinical and pathological parameters of endometrial carcinoma." (PMID 23840707, 2013). "EFEMP1 has been previously shown to suppress the epithelial-mesenchymal transition in endometrial carcinoma through Wnt/β-catenin signaling, for which WNT2B is an activator." (PMID 39607017, 2024). "Fibulin-3, also known as EFEMP1 (epidermal growth factor-containing fibulin-like extracellular matrix protein 1) acts as a tumour suppressor in endometrial cancer." (PMID 36982551, 2023). "Analysis of qRT-PCR assay revealed that expression of mRNA for TOP2A and ASPM are up-regulated in endometrial cancer cells, whereas those of EFEMP1 and FOXL2 are down-regulated." (PMID 32555395, 2020). "We found up-regulation of TOP2A and ASPM in endometrial cancer tissues or cells, while EFEMP1 and FOXL2 were down-regulated." (PMID 32555395, 2020). "Aberrant expression levels of four genes out of 12 core DEGs showed a significant (P < 0.05)association with poor prognosis of endometrial cancer, and this included two up-regulated (TOP2A and ASPM) and two down-regulated (FOXL2 and EFEMP1) genes." (PMID 32555395, 2020). "Our findings showed that EFEMP1 was down-regulated in endometrial cancer tissues, as well as endometrial cancer cell lines." (PMID 32555395, 2020). "On the other hand, HAND2-AS1, PEG3, OGN, SFRP4, WT1, FOXL2 and EFEMP1 were significantly lower in endometrial cancer tissues than in normal tissues." (PMID 32555395, 2020). "Epidermal growth factor-containing fibulin-like extracellular matrix protein 1 (EFEMP1) acted as a tumor suppressor in endometrial carcinoma (EC)." (PMID 27015552, 2016). "In endometrial carcinoma cells, estrogen/ERα signaling significantly suppressed the expression of EFEMP1." (PMID 27015552, 2016). "Our results (which are in line with those reported for endometrial cancer cells) 30 also suggest that, at least in some PCa, EFEMP1 silencing promotes the emergence of an invasive phenotype as well as resistance to apoptosis." (PMID 25211630, 2014). "Compared with normal endometrium (32/40) and atypical hyperplasia (7/10), EFEMP1 expression was much lower in endometrial carcinoma tissues (16/84) (P<0.001 and P = 0.02)." (PMID 23840707, 2013). "EFEMP1 is a new candidate tumor suppressor gene in endometrial carcinoma, and is frequently silenced by promoter hypermethylation." (PMID 23840707, 2013).
endometrial carcinoma (continued). "In completely unmethylated normal endometrium (N1) and endometrial carcinoma (T3), the percentage of methylated CpG dinucleotides was 0% and 3.3% respectively, and showed strong expression of EFEMP1 (IRS10, 12)." (PMID 23840707, 2013). "EFEMP1 promoter was hypermethylated in endometrial carcinoma tissues (67%) as compared to normal tissue (10%) and down-regulation of EFEMP1 was associated with promoter hypermethylation." (PMID 23840707, 2013). "The expression of EFEMP1 was investigated using immunohistochemistry in a panel of normal endometrium (n = 40), atypical hyperplasia (n = 10) and endometrial carcinoma tissues (n = 84)." (PMID 23840707, 2013). "Our present results indicate that promoter hypermethylation is a major mechanism for inactivation of EFEMP1 as a tumor suppressor in endometrial carcinoma." (PMID 23840707, 2013). "The suppressive effects of EFEMP1 on endometrial carcinoma were confirmed by both in vitro and in vivo studies, where cancer cell proliferation, invasion, and migration were found to be impaired." (PMID 23840707, 2013). "In summary, our studies demonstrate the importance of EFEMP1 expression in preventing tumor proliferation and invasion in endometrial carcinoma and show that its expression is mainly regulated by promoter methylation." (PMID 23840707, 2013). "Our observation that inhibition of histone deacetylation by TSA partially relieved transcriptional repression of the methylated EFEMP1 in endometrial carcinoma cells is consistent with this model." (PMID 23840707, 2013). "These paradoxical effects of EFEMP1 in tumorigenesis prompted us to investigate the role of EFEMP1 in endometrial carcinoma." (PMID 23840707, 2013). "Besides, EFEMP1 increased expression of E-cadherin and suppressed expression of vimentin in endometrial carcinoma." (PMID 23840707, 2013). "This new function of EFEMP1 could serve as a predictive biomarker in endometrial carcinoma to predicate endometrial carcinoma." (PMID 23840707, 2013). "In this study, we aim to determine whether EFEMP1 affects the tumorigenesis and progression of endometrial carcinoma." (PMID 23840707, 2013). "Statistical difference between EFEMP1 expression in normal endometrium and endometrial carcinoma." (PMID 23840707, 2013). "However, in endometrial carcinoma, further molecular studies are needed to elucidate the mechanism of EFEMP1 on suppression of tumor metastasis." (PMID 23840707, 2013). "Thus, the purpose of this study was to determine the relationship between the expression of EFEMP1 and endometrial carcinoma, and to explore whether DNA hypermethylation was the mechanism responsible for the dampened expression of EFEMP1." (PMID 23840707, 2013). "To explore the possible mechanisms, which may have contributed to the diminution in expression of EFEMP1, we used MSP and bisulfite genomic sequencing to examine the methylation status of the EFEMP1 promoter in a panel of EC cell-lines, primary endometrial carcinomas, and normal endometrial tissues." (PMID 23840707, 2013). "Studies have shown that estrogen suppresses EFEMP1 and inhibits the Wnt/β-catenin signaling pathway to prevent EMT in endometrial carcinoma." (PMID 39822989, 2025). "In summary, four core genes (TOP2A, ASPM, EFEMP1 and FOXL2) and several interesting pathways involved in endometrial cancer were identified." (PMID 32555395, 2020). "Further validation in endometrial cancer cells showed that indeed TOP2A, ASPM, FOXL2 and EFEMP1 were significantly regulated." (PMID 32555395, 2020). "Results showed a significant down-regulation of EFEMP1 and FOXL2 in endometrial cancer cells." (PMID 32555395, 2020). "Finally, we performed a survival analysis and identified four genes (TOP2A, ASPM, EFEMP1, and FOXL2) that play key roles in endometrial cancer." (PMID 32555395, 2020).